CGAS (cyclic GMP-AMP synthase)
Diseases named in the same sentence as CGAS in open-access papers (continued):
Sharing a sentence is not in itself a finding about the gene and the disease.
cancer (continued). "Emerging evidence has demonstrated that PTMs, including phosphorylation, ubiquitination, palmitoylation, methylation, and lactylation, critically modulate the expression of cGAS and STING in cancer through multiple mechanisms." (PMID 40846966, 2025). "cGAS-STING-stimulated type 1 interferons (IFNs) promote cancer removal, whereas cGAS-STING-induced nuclear factor kappa B (NF-κB) activation and pro-inflammatory cytokine production enhance carcinogenesis and cancer metastasis." (PMID 40786100, 2025). "In the adjacent tissues surrounding the cancer cells, STING and cGAS expression was almost universally high before and after chemotherapy." (PMID 39967410, 2025). "In this review, we present a concise overview of the cGAS-STING pathway, highlighting its significance in HPV infection and HPV-related cancers." (PMID 41142804, 2025). "Recent research has emphasized the role of the cGAS‐STING pathway in various diseases, including cancer, autoimmune conditions, and neuroinflammatory disorders." (PMID 40522023, 2025). "Mechanistically, AOH1996 induced cellular DNA damage, activated the cGAS–STING signaling pathway, suppressed cancer stemness by upregulating p-TBK1 expression, and promoted CD8+ T-cell-recruiting chemokines by stimulating IRF3-mediated transcription." (PMID 41024256, 2025). "Activation of cytosolic dsRNA sensing in this context was shown to cooperate with cGAS/STING-mediated dsDNA sensing, stimulating immune cell migration and cancer cell antigen presentation." (PMID 41188872, 2025). "Emerging evidence has revealed that crosstalk between cGAS-STING and ferroptosis regulates cancer pathogenesis." (PMID 40846966, 2025). "In this review, we first outline the principal components of the cGAS-STING signaling cascade and discuss its role in cancer biology." (PMID 40846966, 2025). "The cGAS-STING pathway, a critical component of the innate immune system, plays a central role in antiviral defense, cancer immunotherapy, autoimmune conditions, and neurodegenerative disorders." (PMID 40697819, 2025). "In parallel, pharmacological agonists targeting key components of the cytosolic DNA sensing pathway, such as cGAS and STING, have demonstrated efficacy in enhancing ICB responses in cancer treatment." (PMID 40565221, 2025). "Considering the role of the cGAS-STING pathway in HPV infection and HPV-related cancers, targeting the cGAS-STING signaling pathway is promising for their treatments." (PMID 41142804, 2025). "The cGAS-STING pathway, emerges as a pivotal target in cancer therapeutics due to its acute activation-induced antitumor immunity." (PMID 41438738, 2025). "The importance of the cGAS-STING pathway extends beyond the antiviral response—it has an important role in recognizing and fighting cancer cells." (PMID 41007722, 2025). "The ROS induces ICD and the released DNA activates the cGAS-STING pathway, generating a strong anti-cancer immune response." (PMID 41246345, 2025). "In summary, the nano platform achieved dual-channel activation of the cGAS–STING pathway with irreversible inhibition of PD-L1 immune checkpoint, thereby enhancing cancer immunotherapy." (PMID 40486836, 2025). "Mechanistically, considering the reproducibility across multiple cancer cell lines, we propose that DSF/Cu activates cGAS-STING signaling pathway via a common way, that is, by generating excessive ROS to induce DNA damage and cytosolic dsDNA leakage." (PMID 39990655, 2025). "Its involvement in pathways such as interferon signaling, RIG-I-like receptors, Toll-like receptors, cGAS-STING, and NF-κB highlights its potential as a target for cancer immunotherapy." (PMID 40061935, 2025). "Taken together, these results indicate that ferroptosis in tumors can activate the cGAS-STING pathway, thereby exerting therapeutic effects against cancer cells." (PMID 40846966, 2025).
cancer (continued). "Emerging studies have also elucidated the metabolic pathways regulating cGAS and STING in cancer, including serine, fatty acid, glucose, purine synthesis, and ATP metabolism." (PMID 40846966, 2025). "The cGAS-STING pathway, usually involved in immune defense, contributes to cancer drug resistance by aiding cancer cell survival during chemotherapy and targeted treatments." (PMID 39949780, 2025). "First, the research background of the cGAS‐STING pathway and nanotechnology is briefly outlined to emphasize the promise of STING agonist‐based nanotherapeutics in cancer immunotherapy." (PMID 40842018, 2025). "The cGAS-STING pathway is a pivotal component of the intracellular immune response to cytosolic DNA, playing a critical role in how cancer cells react to DNA damage by activating immune responses." (PMID 40333779, 2025). "As discussed, the cGAS-STING axis activation triggers IFN-I production, a critical factor in fostering anti-cancer immunity." (PMID 40098962, 2025). "This review discusses the role of the cGAS-STING signaling pathway in HPV infection and HPV-related cancers, as well as potential therapeutic strategies that target this pathway." (PMID 41142804, 2025). "On the basis of these findings, drug-targeted modulation of the crosstalk between cGAS -STING and ferroptosis has emerged as a novel approach for cancer therapy." (PMID 40846966, 2025). "Our research found that PRMT1 methylates the conserved R133 residue of cGAS, preventing its dimerization and further inhibiting cGAS/STING signaling in cancer cells." (PMID 40018367, 2024). "Precise regulation of both immune systems at the same time is more beneficial in the fight against immune‐related diseases, for example, the cGAS–STING pathway has been found to play an important role in infections and cancers." (PMID 39286776, 2024). "The importance of cGAS-STING pathway-induced SASP and its role in cancer immune surveillance has been extensively described in several experimental models." (PMID 38561826, 2024). "For example, in small cell lung cancer (SCLC), a WEE1 inhibitor induced DNA damage in cancer cells, increasing type I interferons, CCL5 and CXCL10 via activation of the cGAS-STING pathway, enhancing the response to PD-L1 blockade." (PMID 38796460, 2024). "The cyclic GMP-AMP synthase (cGAS)–stimulator of interferon genes (STING) pathway, a key component of innate immunity, has emerged as a promising target in cancer treatment." (PMID 39033108, 2024). "In order to see if the cGAS-STING pathway is indeed upregulated in ccRCC as has been shown in our experiments, we analyzed the mRNA expression levels of cGAS and STING in a cohort of patients with ccRCC from the TCGA Pan-Cancer cohort." (PMID 39050705, 2024). "The cyclic GMP‐AMP (cGAS)–stimulator of interferon genes (STING) cascade is crucial in the innate immune system's detection of cytoplasmic DNA14, 15, 16 and in promoting the cancer‐immunity cycle." (PMID 39206412, 2024). "One of the promising approaches for cancer therapy is the inhibition of DNA repair and promotion of DNA damage response (DDR) progression to activate the cGAS-STING pathway." (PMID 39185402, 2024). "The cGAS-STING pathway, a central cytoplasmic double-stranded DNA sensor, is a key pathway by which innate immunity responds to infection, inflammation, and cancer." (PMID 38693472, 2024). "Upon light irradiation, these complexes inflict continuous damage to mitochondrial DNA (mtDNA), the nuclear envelope, and nuclear DNA (ncDNA), triggering the cGAS-STING pathway and promoting a pyroptosis-mediated immune response against cancer." (PMID 39221221, 2024). "These include addressing how aggressive cancer cells, such as CSCs, can uniquely harness CIN to induce pro-tumorigenic cGAS/STING signaling relative to other cells." (PMID 39345336, 2024). "Nonetheless, the impact of cGAS/STING inactivation in the crosstalk between senescence and cancer immune surveillance remains to be fully elucidated." (PMID 38561826, 2024).
cancer (continued). "These structures activate the cyclic GMP–AMP synthase–stimulator of interferon genes (cGAS-STING) pathway, triggering immune signaling and potentially eliminating cancer cells." (PMID 39185402, 2024). "In cancer cells, the DNA double-strand break sensor MRE11 can untether nuclear cGAS from nucleosomes, enabling cGAS activation by dsDNA and suppression of tumorigenesis." (PMID 39704565, 2024). "Given the immunostimulatory potential of the cGAS–STING signaling pathway, development of STING agonists and their application are of the utmost relevance in cancer therapy." (PMID 38525112, 2024). "One pivotal pathway garnering increasing attention is the cyclic GMP-AMP synthase (cGAS)-stimulator of interferon genes (STING) pathway, which serves as a vital regulator of innate immunity with profound implications for cancer immunotherapy." (PMID 39834588, 2024). "The cGAS-STING pathway, a crucial element of the innate immune response, has been identified as pivotal in cancer immunotherapy." (PMID 39170700, 2024). "All these findings suggest that understanding the regulatory mechanism of cGAS-STING pathway and its alternations in different cancer types is crucial for developing new immunotherapeutic strategies." (PMID 39403369, 2024). "This indicates that cGAS/STING signaling is critical for host defense and maintenance of immune homeostasis; pathogens and cancer cells have evolved different strategies to evade this." (PMID 38339107, 2024). "As a potent agonist of cGAS–STING, Mn2+ provides a promising option for NK cell‐based immunotherapy of cancers." (PMID 39206412, 2024). "The microRNA miR-23a/b, which can be found overexpressed in cancer, targets the 3′-UTR of cGAS mRNA." (PMID 38675916, 2024). "For example, ATM depletion makes cancer cells more sensitive to ATR inhibitors or DNA damage, which ensures high levels of IFN expression dependent on the cGAS–STING signaling pathway." (PMID 38630271, 2024). "This regulatory effect of TOP1 on cGAS and PD-L1 in vivo reinforces the potential of TOP1 as a therapeutic target and illustrates the intricate interplay of cellular signaling in cancer progression." (PMID 39156107, 2024). "In conclusion, deep understanding the complex interaction between cGAS-STING signaling and autophagy is crucial for unlocking their potential in cancer therapy." (PMID 40395527, 2024). "In conclusion, studying the antitumor mechanism of the cGAS–STING signaling pathway provides new ideas and directions for treating cancer." (PMID 38525112, 2024). "In recent years, the cGAS-STING pathway has garnered increasing recognition as a potent regulator of chronic inflammatory and metabolic diseases and cancer." (PMID 38164186, 2024). "In response to these cGAS-STING pathway-mediated cytokines, cancer cell fragments/particle-internalized immature DCs differentiate into mature DCs that express CD80 and CD86, as well as robust MHC class II, and exert cross-presentation activity." (PMID 38474078, 2024). "Detection of DNA by cytoplasmic innate immune sensors AIM2, cGAS, and STING leads to a robust immune response that can affect the outcome of inflammatory diseases and cancer." (PMID 38277448, 2024). "Over 20 compounds have already been reported to have cGAS- or STING-inhibitory effects, and activators of the cGAS-STING pathway are being developed as cancer therapeutics." (PMID 38665231, 2024). "The main directions and potential obstacles in the regulating mechanism research and therapeutic drug development of the cGAS–STING signaling pathway for inflammatory diseases and cancers will be discussed." (PMID 38525112, 2024). "When cetuximab (an EGFR target inhibitor) was combined with avelumab (a PD-L1 target inhibitor) to treat NSCLC, the anti-cancer mechanism of these two antibodies partially depended on the activation of the ADCC and cGAS-STING pathways driven by NK cells." (PMID 39464890, 2024).
cancer (continued). "In conclusion, we have proposed AMPs‐based STING agonists and demonstrated a multi‐stimuli activatable peptide nanodrug (MAPN) to precisely activate the cGAS‐STING pathway and block PD‐1/PD‐L1 pathway for effective cancer immunotherapy." (PMID 38233164, 2024). "Here we provide a comprehensive overview of the mechanisms involved in autophagy and cGAS-STING signaling, with a specific focus on the interactions between the two pathways and their importance for cancer." (PMID 38660307, 2024). "In conclusion, dissecting the role of the cGAS–STING signaling pathway in antitumor immunity and tumorigenesis should provide important insights into the search for cancer therapeutic targets." (PMID 38525112, 2024). "Currently, the cGAS-STING pathway has received considerable attention due to its holistic and multifaceted role in cancer immune surveillance." (PMID 38693472, 2024). "In summary, many cGAS–STING signaling pathway inhibitors, agonists, cancer immunotherapy strategies, and agonist drug delivery systems have been reported in recent years." (PMID 38525112, 2024). "Similar to cGAS-STING signaling, the function of autophagy in cancer development and therapy is complex." (PMID 38660307, 2024). "In this review, we illustrate the combination of the cGAS-STING pathway with photothermal, photodynamic and sonodynamic physical methods in cancer therapy." (PMID 39125107, 2024). "The cyclic GMP-AMP synthase (cGAS) and its downstream signalling effector stimulator of interferon genes (STING) play a crucial role in cancer development." (PMID 38361933, 2024). "T‐MPs present DNA fragments from cancer cells to APCs and stimulate the production of IFN‐I by activating the cGAS–STING signaling pathway." (PMID 38525112, 2024). "The cGAS-STING pathway’s integral role in linking innate and adaptive immunity underscores its potential as a target for cancer immunotherapy." (PMID 38545114, 2024). "IFN-I derived from the cGAS-STING axis, either in cancer cells or DC, is capable of activating NK cells, DCs, and macrophages, converging on local inflammatory responses in cancer." (PMID 38474078, 2024). "Manganese (Mn2+), known to enhance dendritic cell-mediated cancer immunotherapy by activating the cGAS-STING pathway, has potential in post-operative cancer management." (PMID 38994034, 2024). "Intensive efforts have been invested to develop cGAS-STING agonists and several STING agonists have shown great promise in cancer immunotherapy in pre-clinical models." (PMID 38177099, 2024). "In this context, the cGAS-STING pathway has gained increasing attention, as it has been shown to promote an immune response to the DNA damaging agents used to treat cancer." (PMID 38659582, 2024). "The cGAS/STING pathway senses chromosomal instabilities, double stranded breaks and fragmented DNA in cancer cells." (PMID 39318624, 2024). "Conversely, cGAS-STING inhibition can impair autophagy by reducing the expression of autophagy-related genes, such as BECN1 and ATG7, in cancer cells." (PMID 39149145, 2024). "Here, PRKN-induced release of mtDNA in the cytosol, a potent DAMP and major cGAS/STING activator, was insufficient to recapitulate an IFN response in cancer." (PMID 39213189, 2024). "These collective data show that low GRB2 levels enable cGAS/STING activation and immune detection of cancer cells." (PMID 38459011, 2024). "Mechanistically, HSAT2,3-enriched cancer EVs induced cGAS-TBK1 innate immune signaling and formation of cytosolic granules positive for double-strand RNAs, RNA-DNA, and cGAS." (PMID 38530366, 2024). "Meanwhile, recent studies have demonstrated a positive correlation between cGAS-STING activation and improved prognosis in chemotherapy and immunotherapy for various cancer types, including NSCLC, colorectal, cervical, breast, and melanoma cancers." (PMID 39834588, 2024).
cancer (continued). "The decreased expression of cGAS and STING in peripheral blood CD8+ T cells of cancer patients underscores the crucial role of these molecules in CD8+ T cell function." (PMID 39834588, 2024). "The cyclic GMP-AMP synthase (cGAS)/stimulator of interferon genes (STING) pathway, which plays a key role in innate immunity, is emerging as a promising therapeutic method for cancer." (PMID 38868091, 2024). "STING is a key element in the cGAS/STING cytosolic sensing pathway and several STING agonists are currently being evaluated as anticancer drugs in the field of cancer immunotherapy." (PMID 39001487, 2024). "With so many years of in‐depth research on cGAS–STING, people have realized that cGAS–STING plays a key role in human diseases, particularly DNA‐triggered inflammatory diseases and cancers." (PMID 38525112, 2024). "Although various PRRs can function in the context of cancer, the recognition of aberrant DNA by the cytoplasmic protein cyclic GMP-AMP (cGAMP) synthase (cGAS) have yielded new insights into the activation of innate immune responses." (PMID 38993569, 2024). "The cyclic GMP-AMP synthase (cGAS)-stimulator of interferon genes (STING) pathway, a vital component of the innate immune system, has emerged as pivotal in cancer immunotherapy." (PMID 39170700, 2024). "RC48 inhibits cancer cell proliferation and enhances the sensitivity of cancer cells to immunotherapy by inhibiting the HER2-mediated cGAS-STING pathway." (PMID 39867908, 2024). "Persistent cGAS-STING signaling, as happens in cancers with chromosomal instability, can lead to decreased interferon release via reduced STING levels as a form of tachyphylaxis." (PMID 38659582, 2024). "This study provided evidence that cGAS phosphorylation by RSK2 is required to interact with chromatin DNA, resulting in growth factor-induced cell transformation and colony growth of cancer cells." (PMID 39424777, 2024). "We hope this review will provide new insights into the synergistic effects of cGAS-STING agonists and new leads for clinical cancer therapy." (PMID 39125107, 2024). "The role of cGAS-STING activation, when paired with existing cancer treatments, poses beneficial potential in maximizing responses." (PMID 37761934, 2023). "This review explores the interactions between the upstream and downstream regulators of cGAS-STING and autophagy-related proteins and their relevant effects on cancer immunity." (PMID 36936940, 2023). "As the most active molecule in cGAS signaling, STING engages in the regulation of drug resistance in various cancers." (PMID 38057852, 2023). "Micronucleation was recently recognized as a key mechanism for cytosolic exposure of chromatin fragments, activation of the cGAS/STING pathway and inflammatory signaling in cancer cells." (PMID 36656721, 2023). "Some anticancer cGAS-STING agonists, such as ADU-S100 (MIW815), MK-1454 and E7766, have been cleared for clinical studies in humans to assess their capacity to mediate cancer progression." (PMID 37162544, 2023). "For example, the cyclic GMP–AMP synthase (cGAS)/stimulator of interferon genes (STING) signaling pathway, that can be critical for protection against infection and in cancer immunotherapy can be inhibited by several HPV proteins." (PMID 38049810, 2023). "With the advancement of basic and clinical research, targeting the cGAS-STING pathway has the potential to provide new strategies and drug combinations for cancer immunotherapy." (PMID 37153627, 2023). "Although complete deactivation of the cGAS-STING pathway in primary tumors is rare, overstimulation of this pathway can paradoxically support cancer growth." (PMID 38139802, 2023). "By triggering the cGAS-STING pathway, the innate immune system can be activated, promoting acquired immunity to fight cancer and thus improving survival." (PMID 36936940, 2023). "Together, these results demonstrated that ATM inhibition leads to cGAS-STING activation and IFNβ signaling in multiple cancer types." (PMID 36778120, 2023).